CGAS (cyclic GMP-AMP synthase)
Diseases named in the same sentence as CGAS in open-access papers (continued):
Sharing a sentence is not in itself a finding about the gene and the disease.
tumor (continued). "The cGAS-STING pathway modulates anti-tumor immunity through multiple mechanisms." (PMID 40520004, 2025). "Thus, we can use both agonists synergistically to enhance the activation of the cGAS–STING pathway to prevent tumor metastasis and recurrence." (PMID 40486836, 2025). "Cytosolic mtDNA then activates cGAS-STING signaling—a critical driver of anti-tumor immunity." (PMID 41144149, 2025). "Taken together, targeting cGAS-STING pathway for reprogramming TAMs in TME might be a promising strategy to enhance anti-tumor immunotherapy." (PMID 40075527, 2025). "Overexpression of TREX1 in tumor cells may avoid the engagement of cGAS pathway by degrading cytoplasmic DNA." (PMID 40831989, 2025). "In contrast to cGAS-deficient tumors, neither changes in tumor growth nor statistically significant effects in T and B cell subsets were observed." (PMID 41419196, 2025). "Nevertheless, the activation of cGAS–STING signaling may also impede tumor growth by activating type 1 IFN and concomitantly promoting anti-tumor immunity." (PMID 40136696, 2025). "Notably, ionizing radiation stimulates cGAS-STING-CCL5 signaling, while PARP inhibitors synergize with CAR-T cells by activating cGAS-STING in tumor cells." (PMID 41573551, 2025). "Furthermore, studies have indicated that telomeric DNA fragments, resulting from telomere damage, can stimulate anti-tumor immune responses through the activation of the cGAS-STING pathway." (PMID 40333779, 2025). "Moreover, the cGAS-STING pathway facilitates complex intercellular communication among multiple immune components within the tumor microenvironment, particularly involving CD8+ T-cells, dendritic cells, and natural killer cells." (PMID 40621423, 2025). "In addition to the genomic DNA derived from tumor cells acting as a ligand, our study provides the first account of how macrophages, under the induction of tumor cells, can trigger the cGAS-STING pathway through the release of mtDNA." (PMID 41031375, 2025). "Therefore, regulating the activation homeostasis of the cGAS-STING pathway is crucial for achieving improved anti-tumor therapeutic outcomes." (PMID 40006729, 2025). "While cGAS/STING is known to exert anti-tumor effects by promoting immune responses, its dysregulation in MPNs may drive excessive inflammation and fibrosis." (PMID 40016346, 2025). "However, cGAS/STING can sometimes aid tumor growth and metastasis, highlighting the importance of targeted therapeutic use." (PMID 39949780, 2025). "Furthermore, BCa, characterised as an immunologically ‘cold’ tumour, shows direct regulation of cGAS–STING signalling by Trp metabolism." (PMID 41275427, 2025). "In addition, owing to the inherent complexity of tumor heterogeneity and etiological diversity, the regulatory functions of cGAS within the tumor microenvironment are multifaceted." (PMID 40470467, 2025). "(2020) indicated that the ATR inhibitor AZD6738 may synergistically enhance the anti-tumor effects of radioimmunotherapy through the activation of the cGAS-STING pathway." (PMID 41438738, 2025). "Additionally, PCM activates the canonical cGAS-STING immune pathway to stimulate the anti-tumor immune system." (PMID 40791799, 2025). "Yet, the current study did not assess the influence of CIN-dependent cGAS–STING signaling activity in EGFR-mutated NSCLC on the tumor immune environment or the efficacy of EGFR-TKI therapy." (PMID 40136696, 2025). "dsDNA in tumor cells can be sensed through the cGAS/STING pathway." (PMID 40858547, 2025). "Additionally, CuB activates the cGAS immune pathway, inducing DNA damage in cancer cells and promoting an anti-tumor immune response." (PMID 39949780, 2025). "A novel self‐assembled nanomedicine (PMDDH) has been developed for the co‐delivery of doxorubicin and metformin, aiming to enhance the anti‐tumor efficacy of doxorubicin while alleviating its cardiotoxicity through the activation of cGAS‐STING and AMPK signaling pathways, respectively." (PMID 40052211, 2025).
tumor (continued). "This upregulation activates the cGAS-PD-L1 pathway, helping tumor cells evade immune detection." (PMID 39949780, 2025). "Activation of the cGAS-STING signaling pathway is bidirectional, causing immune-supporting cells to play antitumor roles, while also producing an immunosuppressive environment that promotes tumor growth and metastasis." (PMID 39975558, 2025). "In addition to the induction of ICD, cuproptosis also has the ability to increase the expression of PD-L1 in tumor cells and activate the cGAS-STING pathway." (PMID 41142419, 2025). "However, compared with other tumour systems, the cGAS–STING pathway exhibits unique context‐dependent properties in urological cancers." (PMID 41275427, 2025). "The cGAS–STING pathway plays a crucial role in initiating the anti-tumor immune response." (PMID 40355720, 2025). "Notably, cGAS can acutely sense tumor-derived DNA, thereby triggering an anti-tumor immune response." (PMID 41235258, 2025). "Tumor heterogeneity affects the efficacy of cGAS-STING-targeted therapies." (PMID 40052963, 2025). "To determine whether PRMT1 induces the polarization of tumor-infiltrating macrophages by regulating the cGAS/STING signaling pathway in GC cells, we cocultured GC cells and macrophages in vitro." (PMID 40858547, 2025). "In cancer research, the cGAS-STING pathway is significant for tumor development and therapy." (PMID 40028324, 2025). "Given that G4 ligands targeting telomeres can induce telomeric damage, it is plausible that these ligands might also activate tumor immune responses through the cGAS-STING pathway." (PMID 40333779, 2025). "Furthermore, the cGAS-STING pathway supports long-term anti-tumor immune memory by activating DCs, potentially preventing recurrence." (PMID 40052963, 2025). "Alternatively, the presence of mitochondrial DNA or anomalous telomere-derived DNA in the tumor microenvironment may act as an external stimulus for cGAS in the phagocytic cells that comprise the tumor bed." (PMID 41007720, 2025). "Another approach involves introducing exogenous DNA into tumor cells to activate cGAS." (PMID 40052963, 2025). "The mechanisms of cGAS‐STING pathway suppression by tumor cells are diverse and might be either direct or indirect." (PMID 40145387, 2025). "However, some studies confirmed the roles of cGAS-STING signaling in HPV-related cancer development through the upregulation of PD-L1 and expansion of Tregs, indicating the tumor-promoting effects of cGAS-STING activation under certain contexts." (PMID 41142804, 2025). "Furthermore, JPI-547 exhibited specific immune modulation in cancer cells with HRD, likely through activation of the cGAS-STING pathway, which is associated with increased tumor immunogenicity and potential responsiveness to immune checkpoint inhibitors." (PMID 40959288, 2025). "In inflammatory conditions, cGAS/STING pathway activation can be beneficial for eliminating tumor cells, and PRMT3’s suppression of this pathway may represent a protective mechanism that cancer cells exploit." (PMID 41583428, 2025). "Tumor-derived DNA, such as DNA from dying tumor cells, can activate the cGAS pathway, which implies that DNASE2 may be involved in this process." (PMID 40282270, 2025). "Notably, the tumor cell-intrinsic cGAS–STING pathway plays a critical role in anti-tumor immunity, and has been shown to enhance the efficacy of cancer immunotherapy in several cancers, including CRC8,10–13." (PMID 40451897, 2025). "The results suggested that the synergistic action of Mn2+ and DOX could ultimately boost the anti-tumor effect by amplifying cGAS/STING activation, which in turn initiate IFN-dependent apoptosis." (PMID 40102383, 2025). "The cGAS-STING signal is crucial for antitumor immunity in tumor cells and immune-competent mice." (PMID 40296918, 2025).
tumor (continued). "By releasing damage-associated molecular patterns (DAMPs) and activating the cGAS–STING pathway, OVs can remodel the immunologically “cold” tumor microenvironment (TME) into an inflamed and immune-responsive phenotype, thereby enhancing CD8+ T-cell infiltration and improving antitumor immunity." (PMID 41451200, 2025). "Therefore, a detailed understanding of the activation status and regulatory mechanisms governing cGAS in specific tumor subtypes is pivotal for rationalizing targeted therapeutic interventions and effective combination treatment strategies." (PMID 40470467, 2025). "We speculated that one potential mechanism contributing to CAF-mediated suppression of anti-tumor immune responses in CRC is the downregulation of tumor cell-intrinsic cGAS–STING expression." (PMID 40451897, 2025). "The cGAS–STING pathway mediates tumour immune surveillance by modulating immune responses." (PMID 41275427, 2025). "In addition, the MP contains the tumor common antigen, which activated the DC by cGas-STING pathway, then promotes the tumor-specific CD8+ T cells antitumor response." (PMID 39925807, 2025). "Oxidized tumor mtDNA acts as an endogenous DAMP to activate the cGAS–STING pathway." (PMID 40486836, 2025). "Loss of cGAS-STING does not cause an increase in spontaneous tumor incidence of either WT or tert-/- zebrafish." (PMID 40490553, 2025). "Additionally, the integration of cGAS‐STING‐targeted nanovaccines with extant tumor immunotherapies exhibits considerable potential for augmenting therapeutic efficacy." (PMID 41476652, 2025). "In addition, tumor-derived DNA sensed by DCs can induce IFN-β secretion via the cGAS-STING pathway, a mechanism further confirmed in murine HCC models." (PMID 40432108, 2025). "Studies have shown that chemotherapeutic agents such as Pt also activate the cGAS–STING pathway, which can be enhanced by damaging DNA in tumor cells and releasing it into the cytoplasm, where it binds to cGAS, activates the cGAS–STING pathway, and improves the effect of immunotherapy." (PMID 40486836, 2025). "Simultaneously, preclinical animal models must also be optimized, as the molecular mechanism by which cGAS-STING combined with bispecific antibodies mediates NK cell killing of tumor cells can be more accurately explored in humanized animal models with a functional human immune system." (PMID 41417876, 2025). "cGAS in tumor cells forms a 2:2 DNA oligomerization complex with dsDNA." (PMID 40356601, 2025). "Furthermore, the nanocarrier's design ensures enhanced tumor targeting and immune modulation through the cGAS‐STING pathway, transforming “cold tumors” into “hot tumors” with improved immune responsiveness." (PMID 40052211, 2025). "Furthermore, investigations are necessary to be acquired to comprehend how these cGAS mutants shape immune responses as tumor progression." (PMID 40104511, 2025). "In conclusion, CAFs can directly downregulate tumor cell-intrinsic cGAS–STING expression in CRC." (PMID 40451897, 2025). "cGAS-STING-TANK-binding kinase 1-interferon regulatory factor 3 (TBK1-IRF3) signaling pathway leads to immune cell-mediated tumor suppression by recognizing DNA released into the cytoplasm during chromosomal instability thereby regulating gene expression and inducing apoptosis." (PMID 40191727, 2025). "The mechanism behind this remains unknown, but tumor cells may accumulate DNA fragments in the cytoplasm, activating the cGAS/STING pathway and subsequently STAT1." (PMID 41367865, 2025). "It is noteworthy that the cGAS–STING–NF‐κB signalling axis exerts a biphasic role in tumours." (PMID 41275427, 2025).
tumor (continued). "These inhibitors can reverse the tumor-promoting effects of chronic cGAS-STING activation." (PMID 40052963, 2025). "For cancer patients, strategies like using miRNA mimics or inhibitors could fine-tune cGAS-STING signaling to enhance anti-tumor immunity while minimizing pro-tumorigenic effects." (PMID 39949780, 2025). "Besides, cGAS activation in tumor cells induces senescence and apoptosis, thereby curtailing excessive tumor cell proliferation." (PMID 40470467, 2025). "Additionally, activation of the cGAS/STING signaling helps suppress the tumor metastasis capacity; as these cells attempt to spread, active STING signaling enhances immune recognition and destruction, thereby restricting the formation of new tumors." (PMID 40149420, 2025). "Notably, chronic cGAS/STING-mediated type I interferon production was shown to stimulate tumour progression and dissemination, via cancer cell-intrinsic and -extrinsic effects." (PMID 41188872, 2025). "Finally, the intrinsic characteristics of tumours set the foundation for the function of cGAS–STING pathway." (PMID 41275427, 2025). "Additionally, we previously reported that tumor cell-intrinsic cGAS–STING expression was significantly higher in mismatch repair-deficient (dMMR) CRC compared to MMR-proficient (pMMR) CRC." (PMID 40451897, 2025). "Our database analyses suggested that HR proteins may modulate anti-tumor immunity through the cGAS/STING pathway." (PMID 41463247, 2025). "In the present study, we aimed to investigate the impact of CAFs on tumor cell-intrinsic cGAS–STING expression in CRC, by analyzing the correlation between tumor cell-intrinsic cGAS–STING expression and the stromal expression of versican (VCAN), an immunosuppressive CAF-specific marker in CRC29,30." (PMID 40451897, 2025). "Statistical analysis of tumor cell-intrinsic cGAS and STING expression, co-cultured with CAFs derived from 10 different patients, demonstrated that CAFs significantly reduced cGAS expression in WiDr cells and markedly suppressed STING expression in WiDr, LoVo, and HCT116 cells." (PMID 40451897, 2025). "In summary, engaging the cGAS-STING pathway within the TME exerts a multifaceted anti-tumor effect." (PMID 40098962, 2025). "Given the importance of CD8+ TSCL cells in anti-tumor immunity, this novel cGAS function of BM-derived cells may represent a target for immunotherapy." (PMID 40227734, 2025). "cGAS-STING axis activity directly promotes tumor cell death." (PMID 40552295, 2025). "cGAS-STING activation in the TME significantly influences tumor immunogenicity." (PMID 40563638, 2025). "Moreover, activation of the cGAS‐STING pathway is associated with increased generation of double‐stranded DNA (dsDNA), reversal of tumor hypoxia, and impairment of DNA damage repair." (PMID 39834553, 2025). "After radiation, Mn2+ is continuously released into tumor tissues to promote DC maturation by activating the cGAS-STING cascade signaling pathway, including inducing the phosphorylation of STING and interferon regulatory factor 3 (IRF3), and upregulating interferon beta (IFN-β) expression." (PMID 40585994, 2025). "Looking at knockout mice, so far, there is no report of premature spontaneous tumor development in cGAS, STING, RLR or IFN-α/β receptor-deficient mice." (PMID 40102400, 2025). "Therefore, targeting the palmitoylation of PD-L1 and the depalmitoylation of cGAS represents a potential novel strategy to enhance the clinical effectiveness of anti-tumor immunotherapy." (PMID 40399304, 2025). "Also, the cGAS-STING signaling pathway has been considered as a therapeutic target because its activation suppresses tumor growth and overcomes resistance to anti-PD-1 therapy." (PMID 41142804, 2025). "This indicates that immunosuppressive CAF-rich CRC might exhibit lower expression of tumor cell-intrinsic cGAS–STING." (PMID 40451897, 2025).
tumor (continued). "Similarly, hollow mesoporous silica-coated MnO nanoparticles are developed for MRI-guided tumor therapy, activating the cGAS-STING pathway and enhancing ROS production." (PMID 40083941, 2025). "The cGAS/STING signaling pathway plays a crucial role in tumor immunotherapy." (PMID 41050083, 2025). "Currently, it seems that there are opposite effects whether cGAS-STING signaling is activated in immune cells or tumor cells." (PMID 41241888, 2025). "Given the significance of the cGAS-STING pathway in tumor immune evasion, we are determined to investigate whether PCBP2 influences Pca growth through this pathway." (PMID 40051782, 2025). "In addition, environmental factors within the tumor, such as hypoxia, oxidative stress, or changes in lipid and glucose metabolism, modulate cGAS-STING activity." (PMID 41007722, 2025). "Furthermore, after X-ray irradiation, Mn-ZIF-8 MNs continuously released Mn2+ in the tumor to enhance cGAS-STING activation." (PMID 40585994, 2025). "PMZFNs drive dual therapeutic mechanisms by inducing ferroptosis that directly kills cancer cells while releasing tumor-associated antigens to trigger ICD and activating cGAS -STING, which amplify the efficacy of ICD through interferon-β production and dendritic cell priming." (PMID 40846966, 2025). "Activation of the cGAS/STING pathway in tumor cells leads to the secretion of various aging-related secretory phenotypes, such as proinflammatory cytokines, chemokines, growth factors, and proteases, ultimately inducing cellular senescence and inhibiting tumor proliferation." (PMID 41050083, 2025). "This is because tumor cells in advanced cancers have adapted to cope with the CIN-induced chronic activation of the cGAS–STING–IFN-I pathway by re-wiring the STING downstream signaling away from IFN-I induction so that IFN-I-mediated immune stimulation is lost." (PMID 40227734, 2025). "In contrast, differential activation of the cGAS–STING pathway between normal and tumor cells may underlie the FLASH effect, potentially inhibiting tumor growth while protecting normal tissues from severe damage." (PMID 40417178, 2025). "In tumor cells, the main cGAS activators are DNA after tumor cell damage and mtDNA." (PMID 41041344, 2025). "Additionally, they have been implicated in tumor immunity modulation, particularly through the activation and immunogenic cell death induction of the cyclic GMP–AMP synthase (cGAS)–stimulator of interferon genes (STING) signaling pathway." (PMID 40333779, 2025). "The activation of cGAS-STING signaling pathway suppressed cancer progression, which was associated with the apoptosis of cancer cells and infiltration of immune cells within the tumor microenvironment (TME)." (PMID 41142804, 2025). "Remarkably, cGAS EV-treated mice rejected a rechallenge with MC38 cells on the opposite flank 50 days after recovery from original tumor inoculation, suggesting that cGAS EV administration induces a systemic antitumor response and the formation of antitumor immune memory." (PMID 38518087, 2024). "Recently, m5C methylation has been demonstrated to affect the activation of innate immune pathways including TLR, cGAS-STING, and RIG-I pathways by modulating RNA function, unveiling new mechanisms underlying the regulation of innate immune responses by tumor cells." (PMID 38807595, 2024). "In addition, suspensions of TCL cell line EL4 were implanted into immunocompetent C57BL/6 mice via subcutaneous injection to evaluate the effect of the cGAS inhibitor RU.521 on tumor suppression and to exclude immune system interference." (PMID 38145335, 2024). "Conversely, other work has shown a tumor-promoting role for the cGAS/STING pathway." (PMID 39544936, 2024).